IDH1 (isocitrate dehydrogenase (NADP(+)) 1)
Diseases named in the same sentence as IDH1 in open-access papers (continued):
Sharing a sentence is not in itself a finding about the gene and the disease.
glioma (continued). "An example of this involves the discovery of the novel oncometabolite 2-hydroxyglutarate (2-HG) in IDH1 mutated glioma." (PMID 25167383, 2014). "IDH1/2 mutation is the most frequent genomic alteration found in gliomas, affecting 40% of these tumors and is one of the earliest alterations occurring in gliomagenesis." (PMID 24877111, 2014). "Similar to glioma, IDH1 and IDH2 mutations are mutually exclusive, though the mutational frequency of IDH in AML is much lower (23%)." (PMID 24622842, 2014). "We investigated the spectrum of IDH1/2 mutations in ALGGs given their critical role as prognostic indicators for a more favorable clinical course compared to IDH wildtype gliomas." (PMID 25257301, 2014). "In gliomas, IDH1 mutation, 1p/19q co-deletion, and MGMT promoter methylation can be routinely assessed and the results of these analyses help to refine the diagnosis and prognosis, and improve the treatment of the affected patients." (PMID 24559763, 2014). "We developed and validated a new real-time quantitative polymerase chain reaction (PCR) assay for single-step detection of IDH1 R132H and 11 rare IDH1/2 mutations in formalin-fixed paraffin-embedded (FFPE) glioma samples." (PMID 24889502, 2014). "The present study demonstrated that glioma cells with mutated IDH1 had higher Brd2 levels and proliferated more slowly than the other two groups." (PMID 24520288, 2014). "Patients with IDH1 mutated gliomas had longer OS and PFS, suggesting IDH1 mutation as a potential prognostic marker in gliomas for Chinese patients." (PMID 23840696, 2013). "It is still not completely understood how IDH1 mutations in gliomas contribute to tumorigenesis and at the same time are correlated to good prognosis as compared to gliomas with wtIDH." (PMID 24252742, 2013). "Lower grade gliomas and a subset of glioblastomas with an IDH1 R132 mutation was strongly related to a good prognosis." (PMID 24278465, 2013). "Kim and colleagues examined low-grade gliomas with wild-type IDH1/2 for mutations in or hypermethylation of TET2." (PMID 24202321, 2013). "A recent report has described multi-specific anti-mutated IDH1/2 mAbs, MsMab-1 and MsMab-2, which are useful for diagnosis of IDH1/2 mutation-bearing gliomas." (PMID 24403254, 2013). "Another breakthrough was the finding of the role of isocitrate dehydrogenase 1 (IDH1) mutation in glioma." (PMID 24278465, 2013). "Though IDH1 mutation frequently occurs and is considered as an early event in gliomagenesis, little is known about its role in the recurrence and progression of gliomas." (PMID 23840696, 2013). "Somatic mutations in Isocitrate Dehydrogenase 1 (IDH1) are frequent in low grade and progressive gliomas and are characterized by the production of 2-hydroxyglutarate (2-HG) from α-ketoglutarate by the mutant enzyme." (PMID 24077805, 2013). "IDH1/2 mutated gliomas show distinct epigenetic profiles, characterised by a high frequency of methylated CpG islands, the “CpG island methylator phenotype” (CIMP)." (PMID 22771539, 2013). "The fact that IDH1 mutations occurred in secondary GBM prompted the same group to determine the frequency of IDH1 mutations in the low-grade gliomas." (PMID 23847760, 2013). "IDH1 mutations have been found in approximately 80% of grades II-III gliomas and secondary glioblastomas but have been found in less than 10% of primary glioblastomas." (PMID 23894344, 2013). "The data suggest that IDH1/2 mutations constitute an early mutational event which affects the cellular epigenetic state in a subset of gliomas and AML, an important consideration for the development of therapeutic agents." (PMID 23847760, 2013).
glioma (continued). "Mutations in glioma almost always involve an arginine-to-histidine conversion at position 132 in the catalytic site of IDH1." (PMID 24252742, 2013). "Recently, the sequencing of human gliomas has identified mutations in the isocitrate dehydrogenase 1 and 2 (IDH1 and IDH2) genes." (PMID 23894344, 2013). "In gliomas, IDH1 mutations were reported as IDH1-R132H (664/716: 92.7%), IDH1-R132C (29/716: 4.2%), IDH1-R132S (11/716: 1.5%), IDH1-R132G (10/716: 1.4%), and IDH1-R132L (2/716: 0.2%)." (PMID 24403254, 2013). "IDH1/IDH2 mutation was detected in 32 primarytumors, with 25 low- grade gliomas and 6 anaplastic gliomas harboring IDH1 mutation and 1 low- grade glioma harboring IDH2 mutation." (PMID 23840696, 2013). "Survival analysis revealed patients with IDH1 mutated gliomas had a significantly longer progression-free survival (PFS) and overall survival (OS)." (PMID 23840696, 2013). "BEAMing analysis was also performed on 4 serum samples from glioma patients with the IDH1 mutation as well as 4 serum samples from healthy controls." (PMID 26082317, 2013). "One interesting correlate of having mutated IDH1 in glioma tumors is that the IDH1-mutant tumors are almost always associated with abundant genome-wide changes in DNA methylation as indicated by widespread hypermethylation of CpG islands." (PMID 23634848, 2013). "IDH1 mutation functions by directly remodeling the epigenome to establish the glioma CpG island methylator phenotype (G-CIMP), inhibiting histone lysine demethylases and causing a block to cellular differentiation." (PMID 24077826, 2013). "Evidence has accumulated in the literature regarding the prognostic impact of IDH1 mutation in gliomas, particularly high grade gliomas." (PMID 23840696, 2013). "The high frequency of mutations in IDH1 suggests an important role for the mutant protein in early glioma development, but the exact underlying oncogenic mechanism is not completely understood." (PMID 24252742, 2013). "Nevertheless, our study has provided further evidence for the prognostic impact of IDH1 mutation in gliomas in general in Chinese patients." (PMID 23840696, 2013). "It is tempting to presume that CIMP in IDH1-mutant gliomas is linked to a failure of 5hmC production in these tumors because TET activity is compromised by 2HG." (PMID 23634848, 2013). "Methylation profiling revealed that GBM samples with low grade glioma-like hypermethylated profiles had a high rate of IDH1 mutations and a better outcome." (PMID 24202337, 2013). "Further analysis performed within the low grade glioma cohort indicated that STK17A remains a significant predictor of survival after correcting for the common genetic glioma alterations of IDH1 mutation and PTEN loss." (PMID 24312360, 2013). "It was identified that the absence of IDH1 expression functions as a powerful diagnostic indicator for EVN-mimicking gliomas." (PMID 24179531, 2013). "The frequency of IDH1 mutation was significantly higher in PDGFRA-high gliomas compared to PDGFRA-low gliomas." (PMID 23630597, 2013). "Although the mechanism through which IDH1/2 mutations transform cells is far from clear, gliomas with IDH1 mutations show a significantly higher frequency of the CpG island methylator phenotype as well as increased histone demethylation." (PMID 23762610, 2013). "The staining pattern of mutated IDH1/2 by MsMab-1 looks very heterogeneous, which is different from that of glioma tissues." (PMID 24403254, 2013). "We propose that this model will be of high value for investigating novel therapies for the large group of gliomas that carry IDH1-R132H mutations." (PMID 24252742, 2013). "These gliomas were significantly associated with frequent IDH1 mutation, younger age at disease onset and better survival outcome compared to the gliomas with lower levels of PDGFRA expression." (PMID 23630597, 2013). "Genomic sequencing has also led to the identification of mutations of the isocitrate dehydrogenase genes (IDH1/2) in human gliomas." (PMID 24086756, 2013).
glioma (continued). "Recently, however, a glioma cell line carrying an endogenous IDH1 R132H mutation was published, but this cell line showed a slow growth rate in culture." (PMID 22928481, 2012). "More recently, point mutations affecting metabolic proteins such as IDH1 or IDH2 have been found in the majority of infiltrating gliomas and a subset of glioblastomas." (PMID 22298889, 2012). "Frequent somatic hotspot mutations in isocitrate dehydrogenase 1 (IDH1) have been identified in gliomas, acute myeloid leukemias, chondrosarcomas, and other cancers, providing a likely avenue for targeted cancer therapy." (PMID 22885298, 2012). "In the present study, we reviewed a series of 528 cases of gliomas retrospectively and compared regional constituents of pathological subsets, regional incidences of 1p/19q co-deletion and IDH1/2 mutation." (PMID 22427879, 2012). "As expected, we found that gliomas with the IDH1 mutation tend to have lower GNS signature scores than IDH1 wild-type gliomas of the same histological grade." (PMID 23046790, 2012). "The incidence of IDH1/2 mutation in gliomas of parietal origin (43.3%) showed a trend to be lower than that of non-parietal origin (60.4%) (P = 0.073)." (PMID 22427879, 2012). "Large-scale analyses of genome-wide DNA methylation patterns in human gliomas found that IDH1/2 mutations were associated with a highly specific DNA methylation profile." (PMID 22885298, 2012). "Within the numbering of the human IDH2 sequence, mutations in Arg172 (an analog of frequently mutated Arg132 of cytosolic IDH1) are detected in gliomas, and mutations in Arg172 and Arg140 (which is adjacent in the active site to Arg172) are found in AML." (PMID 22675360, 2012). "IDH1 mutations are an early event in tumorigenesis, and an independent favorable prognostic marker in human gliomas." (PMID 22291938, 2012). "Preferential distribution of pathological subsets, 1p/19q co-deletion and IDH1/2 mutation were confirmed in some brain regions in Chinese glioma patients, implying their distinctive tumor genesis and predictive value for prognosis." (PMID 22427879, 2012). "In pediatric gliomas, IDH1/2 mutations are almost exclusively seen in adolescents who indeed do not represent the target population of DIPG." (PMID 22389665, 2012). "A large proportion of low grade gliomas and a smaller fraction of glioblastomas show mutations in the isocitrate dehydrogenase genes (IDH1 or IDH2)." (PMID 22829908, 2012). "To determine the efficacy of this technology, we assayed CSF microvesicles from patients with glioma tumors, which had been typed for a dominant mutation (G395A) in the isocitrate dehydrogenase (IDH1) gene." (PMID 26082068, 2012). "Consequentially, this raises questions regarding the capacity of IDH1 mutation for use as a prognostic or predictive marker for customized treatment in glial tumors in the near future." (PMID 22291938, 2012). "The incidence of IDH1/2 mutation in gliomas of the temporal origin (41.7%) was significantly lower than that of non-temporal origin (63.2%) (P = 0.003)." (PMID 22427879, 2012). "In this regard, some of the intriguing examples include IDH1 G395 mutations in high grade glioma, which have recently been detected in EV preparations from GBM culture medium and CSF." (PMID 22934045, 2012). "It has been reported in gliomas, isocitrate dehydrogenase mutation 1 (IDH1) is associated with DNA methylation phenotype." (PMID 22666451, 2012). "Variants of the CCDC26 and PHLDB1 genes have predominantly been associated with low grade glioma, and there is a clear correlation between these variants and IDH1 mutation status." (PMID 23236348, 2012). "Recent studies suggest that IDH1 R132 mutations are present in the majority of common adult gliomas but only occur in small fraction of pGBMs, and patients with IDH1 mutation have a better outcome than those with wild-type IDH1 in gliomas." (PMID 22291938, 2012).
glioma (continued). "Patients with diffusely infiltrative gliomas carrying an IDH1 mutation have a significantly longer overall survival compared to patients with IDH1 wild type." (PMID 22427879, 2012). "Mutations in the IDH1-encoding gene are sufficient to establish the glioma hypermethylator phenotype, a powerful determinant of glioma pathogenicity." (PMID 22988443, 2012). "Nevertheless, the most recent studies further suggested that IDH1/2 mutations were associated with a distinct DNA hypermethylation phenotype in gliomas." (PMID 22291938, 2012). "The observed methylation in gliomas reminisces the reports of existence of G-CIMP which was tightly associated with IDH1 mutation and exhibited better prognosis." (PMID 22666451, 2012). "Pathological constituents of tumor subsets, incidences of 1p/19q co-deletion and IDH1/2 mutation in gliomas by regions and sides in the brain were analyzed." (PMID 22427879, 2012). "IDH1 is a [NADP + ]-dependent cytosolic enzyme that is mutated in 80% of grades II–III gliomas and secondary glioblastomas." (PMID 26082068, 2012). "Monoallelic expression of IDH1 has recently been reported in 12 out of 67 gliomas with IDH1 mutations, with expression occurring only from the wildtype allele in 10 of 12 cases." (PMID 23267435, 2012). "Conversely, genomewide mutation analyses and high-throughput deep sequencing revealed the presence of mutations in either IDH1 or its mitochondrial counterpart IDH2 in 70% of grade II-III gliomas and secondary glioblastomas." (PMID 22888353, 2012). "Although the mechanism is unclear, IDH1/2 mutations are thought to represent an early event in gliomagenesis and have been associated with a glioma-CpG island methylator phenotype (G-CIMP) and improved prognosis in glioblastoma." (PMID 22829908, 2012). "IDH2 and IDH1 mutations occur frequently in certain types of World Health Organization grade 2–4 gliomas and in AML cases with a normal karyotype." (PMID 23226729, 2012). "Two gliomas in our cohort were found to harbor IDH1 mutations when subjected to DNA sequencing, but exhibited no protein expression by immunohistochemistry, despite repeated testing." (PMID 23267435, 2012). "This study provided a detailed incidence map of glioma subsets (relative), 1p/19q co-deletion and IDH1/2 mutation cross the brain in Chinese patients." (PMID 22427879, 2012). "The distribution of IDH1/2 mutation resembles that of 1p/19q co-deletion and provided another evidence for the distinctiveness of gliomas from different brain lobes." (PMID 22427879, 2012). "And it has been reported that patients with IDH1 mutation were also sensitive to Temozolomide (TMZ) in low-grade gliomas." (PMID 22291938, 2012). "Heterozygous somatic mutations in IDH1 occur at codon 132 in 70% of grade II–III gliomas and secondary glioblastomas (GBMs), and in 5% of primary GBMs." (PMID 21625441, 2011). "We have found that TMEFF2 hypermethylation is associated with non-Proneural subtypesof GBMs, in contrast with G-CIMP methylation and IDH1 mutation status, which areassociated with the Proneural subtype and lower-grade gliomas." (PMID 21559523, 2011). "Affected cancer types include gliomas of intermediate malignant grade (73–94%) and acute myeloid leukemias (AMLs, 16–22%), and cases of IDH1 mutations have been reported in prostate cancer, acute lymphoblastic leukemia, B type, colorectal cancer, and melanoma." (PMID 21326614, 2011). "Gliomas frequently contain mutations in the cytoplasmic NADP+-dependent isocitrate dehydrogenase (IDH1) or the mitochondrial NADP+-dependent isocitrate dehydrogenase (IDH2)." (PMID 21326614, 2011). "IDH1 mutations occur in approximately 60 - 80% of diffusely infiltrating gliomas of the WHO grades II and III and in secondary GBM but only in around 5% of primary GBM." (PMID 21910919, 2011). "IDH1 mutations segregate in proneural type GBMs or in gliomas containing predominantly secondary GBMs (Cluster 22) as well as in gliomas with more favorable prognosis (Clusters 9 and 17)." (PMID 24212656, 2011).
glioma (continued). "Nonetheless, as normal cells seem to be more congruous to the standard cell culture conditions than glioma cells with IDH1 mutation, the factors responsible for the elimination of glioma cells in vitro should be identified for possible pharmacological use." (PMID 21326241, 2011). "IDH2 is homologous to IDH1, and IDH2 mutations in glioma are specific for R172, the residue that is analogous to IDH1 R132." (PMID 21326614, 2011). "So far, mutations of IDH1 have been detected almost exclusively in glial tumours, including astrocytomas and secondary glioblastomas, but not in primary glioblastomas." (PMID 21326241, 2011). "Mutations in IDH1 and the clinical implications of this biomarker for gliomas have received considerable attention lately." (PMID 21559010, 2011). "IDH1 mutations are an early event in tumorigenesis, are an independent favorable prognostic marker in gliomas and are closely associated with1p19q codeletion and MGMT methylation status." (PMID 24212656, 2011). "The IDH1 mutation is expected to be almost mutually exclusive with EGFR amplification, so glioma cells with IDH1 mutation seem to represent a new group of tumour cells, which cannot be readily analysed in vitro because of their elimination." (PMID 21326241, 2011). "Recent studies reported that mutations usually affected amino acid 132 of IDH1 in more than 70% of grade II-III gliomas and secondary glioblastomas." (PMID 21575270, 2011). "If this glutamate-dependent acetyl-CoA generation pathway functions in glial cells, in gliomas the mutations of IDH1 or the low amounts of MDH1 are expected to reduce the concomitant production of acetyl-CoA and oxaloacetate through this pathway." (PMID 21655185, 2011). "Further investigation with larger sample sizes will aid in discerning the diagnostic utility of T with respect to IDH1 typing in glioma and may reveal additional insight of the sensitivity of T to time‐dependent changes." (PMID 41436375, 2026). "Because reasons for drop-out and the clinical status were unknown at time of attrition we cannot conclude whether e.g., early progression has biased the long-term results, although unlikely in a 12 month follow-up in IDH-1 mutated glioma." (PMID 41514682, 2026). "Clinical validation has confirmed that this dual-channel synergistic detection strategy can accurately identify the IDH1.R132H mutation in glioma patients with as little as 1 μL of sample, and deliver crucial clinical information such as tumor size and staging." (PMID 42043839, 2026). "While future studies amending these constraints may better characterise the diagnostic utility of T for IDH1 typing in glioma, this preliminary investigation lends promise to its efficacy." (PMID 41436375, 2026). "IDH1/2 mutations (IDHmut) increase methylation of DNA and histones in gliomas." (PMID 41066183, 2025). "TSPYL1, a chromatin remodeling factor, is associated with neural development and may contribute to glioma progression, as identified in IDH1-associated tumor evolution studies." (PMID 40725410, 2025). "This discrepancy may reflect the inclusion of tumors arising from undiagnosed lower-grade gliomas, where IDH1 mutations occur in 73–88% of cases." (PMID 40261557, 2025). "IDH1 mutations are common in low-grade gliomas (80%) but are rare in primary glioblastomas (4%)." (PMID 40718831, 2025). "In addition, mutations in IDH1/2 genes, commonly occurring in glioma and AML and less frequently in other tumors, lead to elevated 2HG." (PMID 40073141, 2025). "Patients with gliomas harbouring IDH1 or IDH2 mutations have been shown to have a decreased risk of thromboembolism, which may be related to a decreased expression of tissue factor, leading to a decrease in coagulation system activation." (PMID 40862818, 2025). "IDH1 mutation is a major event in lower-grade glioma, with a mutation rate ranging from 65-90%." (PMID 40190555, 2025).